SYNCRIP (synaptotagmin binding cytoplasmic RNA interacting protein)
Description:
Heterogenous nuclear ribonucleoprotein (hnRNP) implicated in mRNA processing mechanisms. Component of the CRD-mediated complex that promotes MYC mRNA stability. Isoform 1, isoform 2 and isoform 3 are associated in vitro with pre-mRNA, splicing intermediates and mature mRNA protein complexes. Isoform 1 binds to apoB mRNA AU-rich sequences. Isoform 1 is part of the APOB mRNA editosome complex and may modulate the postranscriptional C to U RNA-editing of the APOB mRNA through either by binding to A1CF (APOBEC1 complementation factor), to APOBEC1 or to RNA itself. May be involved in translationally coupled mRNA turnover. Implicated with other RNA-binding proteins in the cytoplasmic deadenylation/translational and decay interplay of the FOS mRNA mediated by the major coding-region determinant of instability (mCRD) domain. Interacts in vitro preferentially with poly(A) and poly(U) RNA sequences. Isoform 3 may be involved in cytoplasmic vesicle-based mRNA transport through interaction with synaptotagmins. Component of the GAIT (gamma interferon-activated inhibitor of translation) complex which mediates interferon-gamma-induced transcript-selective translation inhibition in inflammation processes. Upon interferon-gamma activation assembles into the GAIT complex which binds to stem loop-containing GAIT elements in the 3'-UTR of diverse inflammatory mRNAs (such as ceruplasmin) and suppresses their translation; does not seem to be essential for GAIT complex function.
Synonyms: GRY-RBP; NSAP1; dJ3J17.2; HNRPQ1; hnRNP-Q; HNRNPQ; GRYRBP; PP68
Tractability: PROTAC: UniProt records ubiquitination sites on it; ubiquitination databases record sites on it; its protein half-life has been measured.
Gene: Protein-coding gene on chromosome 6 (85,607,779 to 85,644,063, reverse strand). Ensembl gene ENSG00000135316.
Subcellular location: Cytoplasm; Microsome; Endoplasmic reticulum; Nucleus; Nucleus, nucleoplasm (Isoform 1); Nucleus, nucleoplasm (Isoform 2); Nucleus, nucleoplasm (Isoform 3)
Subcellular location (Human Protein Atlas): Nucleoplasm; Cytosol; Vesicles
Gene Ontology:
Molecular function: protein binding; RNA binding; mRNA 5'-UTR binding; nucleic acid binding
Biological process: cellular response to type II interferon; CRD-mediated mRNA stabilization; negative regulation of nuclear-transcribed mRNA catabolic process, deadenylation-dependent decay; negative regulation of translation; osteoblast differentiation; positive regulation of cytoplasmic translation; mRNA splicing, via spliceosome; negative regulation of formation of translation preinitiation complex; RNA processing; RNA splicing
Cellular component: catalytic step 2 spliceosome; CRD-mediated mRNA stability complex; cytoplasm; cytosol; GAIT complex; mCRD-mediated mRNA stability complex; membrane; ribonucleoprotein complex; histone pre-mRNA 3'end processing complex; nucleus; endoplasmic reticulum; nucleoplasm
Genetic constraint (gnomAD): Loss-of-function variants: 9 observed, 63.11 expected, observed/expected ratio (o/e) 0.14, 90% interval 0.085 to 0.25. The upper end of that interval is the gene's LOEUF score, 0.25, which puts it in group 1 of 6, group 1 being the genes least tolerant of losing a copy. Missense variants: 399 observed, 766.98 expected, observed/expected ratio (o/e) 0.52, 90% interval 0.48 to 0.56. Synonymous variants: 251 observed, 252.22 expected, observed/expected ratio (o/e) 1, 90% interval 0.9 to 1.11.
Gene-disease validity (ClinGen):
ClinGen rates the evidence that SYNCRIP causes each of these diseases.
SYNCRIP-related neurodevelopmental disorder (autosomal dominant): Definitive. Any neurodevelopmental disorder in which the cause of the disease is a variation in the SYNCRIP gene.
Homologues: Orthologues: pig SYNCRIP (99% identical), mouse Syncrip (99% identical), tropical clawed frog syncrip (92% identical), macaque SYNCRIP (91% identical), rat Syncrip (90% identical), chimpanzee SYNCRIP (89% identical), dog SYNCRIP (89% identical), guinea pig SYNCRIP (89% identical), zebrafish syncrip (88% identical), zebrafish syncripl (75% identical). Paralogues in human: HNRNPR (84% identical), PABPC4 (17% identical), PABPC1 (16% identical), PABPC3 (16% identical), PABPC1L (15% identical), RBMS1 (14% identical), RBMS3 (14% identical), RBMS2 (14% identical), ELAVL4 (13% identical), ELAVL2 (13% identical), ELAVL3 (13% identical), SF3B4 (12% identical), and 12 more.